LINC01770 (long independently transcribed non-coding RNA 1770)
Synonyms: RRFERV
Gene: Long non-coding RNA gene on chromosome 1 (1,429,194 to 1,435,625, reverse strand). Ensembl gene ENSG00000225285.
Diseases named in the same sentence as LINC01770 in open-access papers:
LINC01770 is named in the same sentence as 1 disease in open-access papers, as found by Europe PMC text mining. Sharing a sentence is not in itself a finding about the gene and the disease. The quoted sentences say what the papers report.
endometrial cancer (1 paper, 2023). Primary or metastatic malignant neoplasm involving the endometrium (mucous membrane that lines the endometrial cavity). "LINC01770 is upregulated in endometrial cancer in comparison with endometrial dysplasia tissues." (PMID 37445988, 2023).